TNF (tumor necrosis factor)
Diseases named in the same sentence as TNF in open-access papers (continued):
Sharing a sentence is not in itself a finding about the gene and the disease.
Thrombocytopenia (continued). "Finally, our findings reveal a pattern of MIS-C-defining molecular features (IL15/IL15RA, MIP1α, TNFα, and IL1 pathways) and clinical and laboratory parameters (thrombocytopenia, eosinopenia, and reduced myocardial function)." (PMID 35577777, 2022). "In contrast, PedSep-D had the most profound inflammatory response with highest M-CSF, IL-8, SCF, sCD163, IL-16, IL-10, TNF, and MIP1α levels, and thrombotic microangiopathic response with lowest ADAMTS13 activity decreased to < 57% of control with thrombocytopenia." (PMID 35526000, 2022). "TLR4 is involved in rapid TNF-α induction, NET formation, and thrombocytopenia." (PMID 31379873, 2019). "As observed with G-1180, the marked absence of TNF-α, a potent inducer of endothelial damage via apoptosis and thrombocytopenia, throughout the monitored course of G-1442's illness, suggests a regulated and effective immune response at play." (PMID 21843352, 2011). "Additionally, a high IL-10 to TNF-α ratio, combined with thrombocytopenia, constitutes a non-specific marker of acute leptospirosis in symptomatic and asymptomatic infections." (PMID 40732660, 2025). "However, the patient in Case 1 and 2 did not develop fatal thrombocytopenia despite the long-term use of TNF inhibitors." (PMID 34660652, 2021). "In mild-grade CLP, clopidogrel- and vehicle-treated mice did not display a significant decrease in MAP, while thrombocytopenia and plasma concentrations of TNFα, IL6, IL10, MPO, TAT and organ damage reached similar levels in both groups, although lower than those reached in the high grade CLP." (PMID 34447900, 2021). "However, no case of thrombocytopenia was observed in patients treated with anti-TNFα BTs." (PMID 35651659, 2022). "Notably, the marked absence of TNF-α, a potent inducer of endothelial damage via apoptosis and thrombocytopenia throughout the monitored course of illness in G-1180, with the exception of a spike on day10, suggests a somewhat regulated and effective immune response at play." (PMID 21689444, 2011). "The degree of thrombocytopenia and hemoconcentration was similar in WT and CCR2–/– mice, but levels of IL-6 and IFN-γ, but not TNF-α, were decreased systemically in infected CCR2–/– mice." (PMID 21206747, 2010).
Fever (87 papers, 2008 to 2026). Body temperature elevated above the normal range. "Other pro-inflammatory cytokines, such as TNF-α, IL-1β and IL-6, are thought to be associated with fever and multi-organ dysfunction in HLH." (PMID 40842582, 2025). "This marked production of potent endogenous pyrogens such as IL-1β, IL-6 and TNF-α, can interact directly with the anterior hypothalamus, through a hierarchy of neural structures, and raise the temperature setpoint, causing fever." (PMID 39928662, 2025). "This instant acute-phase reaction resulting in pyrexia, exhaustion or chills is thought to be caused by the release of pro-inflammatory cytokines, such as IL-6 and TNF-a." (PMID 34018012, 2022). "Consistent with this, expression of CyHV-3 ORF12, encoding a soluble decoy receptor for TNF-α, delayed the manifestation of behavioral fever and promoted CyHV-3 replication in the context of a temperature gradient." (PMID 28182952, 2017). "These activated cells released proimflammatory cytokines such as TNF-α, IL-1 and IL-6, which could cause fever, hyperferritinemia and other symptoms." (PMID 28196537, 2017). "During heat stress, body temperature increases and homeostasis of the intestinal flora becomes disrupted, which may cause inflammatory factors such as TNF-α, IL-6, IL-8, among others, to be released into the circulation, which can lead to fever." (PMID 27857180, 2016). "The fever group had significantly increased serum levels of TNF-α, IL-1β, IL-6 and PTGS2 (p < 0.05, p < 0.01) compared to the control group." (PMID 40430430, 2025). "Fever was induced using turpentine, an exogenous pyrogen that stimulates endogenous pyrogens such as TNF-α, interferon-gamma (IFN-γ), IL-1β, and IL-6 to initiate the synthesis of PGE2." (PMID 41245555, 2025). "Accordingly, several other studies reported the anti-inflammatory effect of borneol, by showing its capacity to inhibit pro-inflammatory mediators such as NO, TNF-α and IL-6 in LPS-stimulated macrophages and by decreasing fever in a model of endotoxic fever." (PMID 36671380, 2023). "In a lipopolysaccharide-induced fever rodent model, researchers observed a lower fever and lower pro-inflammatory cytokines IL-1β and TNFα in animals pre-treated with KD compared to controls, although ketone body measures were not included." (PMID 37936721, 2023). "TPDM6315 reduced the nitric oxide production and expressions of the COX2, PGE2 TNF-α, and IL-6 genes, indicating a possible anti-inflammatory effect of this recipe, which has been traditionally used to treat fever." (PMID 37367060, 2023). "Fever is a common brain-mediated antitraumatic, infective, or non-infective inflammatory response mediated by endogenous pyrogens such as IL-6, TNF-α, PGE2, corticotropin-releasing factor, and endothelin-1." (PMID 35736412, 2022). "The incidence of pyrexia involves many mediators, such as interleukins IL-6, IL-1β, IL-8, and TNF-α, as recorded in previous studies." (PMID 34641376, 2021). "In order to explore the antipyretic effect of HLJDD on LPS-induced fever in rats, we detected the expression levels of TNF-α and IL-6 in the serum and PGE2 and cAMP in the hypothalamus tissue of fever rats." (PMID 35003291, 2021). "Fever is known to be caused by several endogenous pyrogens such as interleukin-1β (IL-1β) and IL-6, interferon-α (IFN-α), tumor necrosis factor-α (TNF-α), macrophage protein-1, and prostaglandins such as PGE2 and PGI2." (PMID 33747115, 2021). "The activities of IL1β and IL6 are similar to TNF-α, including the induction of pyrexia and the production of acute phase proteins." (PMID 31918707, 2020). "Fever is among the most common systemic clinical signs during infection and is mediated by the release of pyrogenic cytokines such as TNF-α and IL-63." (PMID 32221396, 2020). "The occurrence of pyrexia involves numerous nerval routes and factors, such as interleukin 6 (IL-6) and tumor necrosis factor alpha (TNF-α)." (PMID 31143120, 2019).
Fever (continued). "Fever is typically induced by the production of pro-inflammatory cytokines, such as TNF-α and IL-1β, during LPS immune challenge." (PMID 30841603, 2019). "Accumulating evidences, obtained from animal model studies, suggested that the levels of TNF-α and IL-6 were increased following yeast-induced fever." (PMID 31143120, 2019). "Of note, high levels of L-valine were observed in pyrexia rats with accumulated expression of IL-6 and TNF-α." (PMID 31143120, 2019). "TNF-α is another important cytokines that has roles in anti-tumor and proinflammatory responses, pyrexia, inhibition of viral replication, and activation of monocytes." (PMID 30894844, 2019). "Elevated IL-8 (CXCL8) level results in only transient pyrexia and less pathogen bacteria shedding of Salmonella-infected pigs while increased TNF-α level can lead to prolonged inflammatory condition and persistent pathogen shedding." (PMID 30718974, 2019). "The pro-inflammatory cytokine interleukin-1β serves as the main endogenous pyrectic substance in initiating fever and works synergistically with interleukin-6 and TNF-α." (PMID 31174289, 2019). "show that a carp herpesvirus delays behavioral fever by expressing a soluble decoy receptor for TNF-α, thus promoting its own replication." (PMID 28182952, 2017). "We demonstrate the ability of this virus to alter this behavior of its host through the expression of a single gene and identify the role of TNF-α as a mediator of behavioral fever in ectotherms." (PMID 28182952, 2017). "Injection of LPS induces fever in pigs by stimulating the production of cytokines such as IL-1, TNF-α and IFN-γ, which are regarded as endogenous mediators of fever." (PMID 27822369, 2016). "Three days following anti-TNF treatment, he became drowsy, and examination revealed pyrexia, slurred speech, and nystagmus." (PMID 27651962, 2016). "Inhalation of ultrafine ZnO was found to be the major cause of zinc fume fever that is characterized by increased neutrophils in BAL fluid, along with an increase in TNF-α, IL-1, and IL-8, followed by decreased lung function, cough, fever, and metallic taste." (PMID 24684892, 2014). "Fever is triggered by the release of various cytokines, notably IL-1, IL-6 and TNFα which in turn can affect the immune response and defense mechanisms in a complex way." (PMID 23351502, 2012). "Fever is induced by pro-inflammatory cytokines such as interleukin (IL)-1β, IL-6, and tumor necrosis factor (TNF)-α during infections." (PMID 21989210, 2011). "One of the characteristic systemic responses related to TNFα administration is pyrexia or increase in body temperature." (PMID 20463923, 2010). "Similarly, Atlantic salmon (Salmo salar) infected with infectious pancreatic necrosis virus (IPNV) exhibited behavioral fever, increasing their preferred temperature and upregulating pro-inflammatory cytokines (IL-1β, IL-6, TNF-α)." (PMID 40508975, 2025). "Fever is known to be the most frequent symptom of cytokine storms, mainly associated with the over-activation of neutrophils, monocytes, macrophages, T cells and massive release of cytokines (such as IL-6, IL-2, IFN-γ, TNF-α)." (PMID 39127636, 2024). "In our experiments, it was confirmed that SHL could reduce the pro-inflammatory cytokines TNF-α, IL-6, and IL-1β in LPS-induced fever rats in order to play an antipyretic and anti-inflammatory effect." (PMID 35837285, 2022). "The APP response governs a cascade of pathological responses resulting in leukocytosis, elevation of acute reactive proteins (e.g., D-dimer, CRP, serum amyloid A, interleukins, tumor necrosis factor α), as well as clinical responses (e.g., pyrexia, hormonal alterations, muscle protein depletion)." (PMID 32864251, 2020). "Fever is a manifestation of multiple pathways including the release of pro-inflammatory cytokines (including interleukin (IL)-1, IL-6, and tumor necrosis factor (TNF)-alpha) as a consequence of infection or inflammation." (PMID 31222393, 2019).
Fever (continued). "In addition, they demonstrate a role for TNF-α in the induction of behavioral fever in teleost fish." (PMID 28182952, 2017). "An interesting perspective would be to investigate whether the homology existing between the cytokine signaling pathways of behavioral fever in ectotherms and fever in endotherms extends to cytokines other than TNF-α." (PMID 28182952, 2017). "Here, we identified the role of carp TNF-α as a key mediator of behavioral fever in an ectotherm." (PMID 28182952, 2017). "Here we present a case history of a patient with RA who had an episode of acute Q fever while being treated with anti-tumor necrosis factor-α (anti-TNFα) medication, and who developed probable chronic Q fever over the subsequent two years while using the anti-B-cell monoclonal antibody rituximab." (PMID 24931640, 2014). "Fever is an immune response initiated by inflammatory mediators such as interleukin (IL)-1, IL-6, tumor necrosis factor (TNF)-α, macrophage inflammatory protein 1, and interferon (IFN) for heat production, and depends on antipyretics (IL-10, glucocorticoids, and neuropeptides) for heat dissipation." (PMID 25228909, 2014). "In summary, TNF appeared in the plasma before the onset of symptoms, IL-6 was detected as symptoms developed, and IL-8 was detected in plasma well after the onset of rigor and pyrexia." (PMID 24198733, 2013). "A decade and a half ago, detailed analysis of cytokine release in the early phase of JHR showed that TNF concentration increases within 30 min following penicillin administration and that this increase preceded pyrexia and the rises in plasma IL-6 and IL-8 concentrations." (PMID 24198733, 2013). "Hyperthermia and fever are initiated following exposure to exogenous (bacteria, toxin) or endogenous pyrogens (pro-inflammatory cytokines (IL-1β, IL-6 and tumor necrosis factor-α (TNF-α))." (PMID 22971439, 2012). "Under fever conditions, different kinds of endogenous anti-inflammatory cytokines are induced, both pyrogenic such as IL-1α and -β, IL-6, IL-8 and interferon-γ (IFNγ), and antipyretic, such as IL-10 and TNFα." (PMID 23166650, 2012). "Our study shows that TNFα-induced pyrexia was inhibited when PLD1 was knocked down." (PMID 20463923, 2010). "Interestingly, it has also been reported that TNFα-induced pyrexia in mice was largely mediated by IL-6 production." (PMID 20463923, 2010). "This syndrome is characterized by the presence of pyrexia, tachycardia, hypotension, tachypnea, myalgia, transient confusion, delirium, aphasia, and seizures, among other symptoms mimicking sHLH in our case, and it is secondary to high amounts of TNF-a and IL-6 being released." (PMID 36195892, 2022). "NF-κB is a transcription factor activated by TLR agonists and cytokines, such as TNF-α, and is thought to be a key regulator of neuroinflammation and fever, since NF-κB-deficient mouse do not develop a fever after LPS injection." (PMID 31920538, 2019). "The dispersion estimates results showed that the difference in the expression of IL6R, TNF-α and PTGS2 between the normal group and the fever group was statistically significant (p < 0.01)." (PMID 40430430, 2025). "Therefore, the inflammation‐suppressive action of the bioactive components of Fevogrit could well be the primary mode of action of Fevogrit against LPS‐induced fever, as shown by the reduced levels and gene expression of TNF‐α, IL‐1β and IL‐6 in serum and hypothalamus, respectively." (PMID 39021318, 2025). "In mice fever models, ADHP1 demonstrated marked antipyretic efficacy through dual suppression of pro-inflammatory cytokines (IL-1β, TNF-α) and prostaglandin biosynthesis." (PMID 40633473, 2025). "Compared with the normal group, the expression levels of IL6R, TNF-α, and PTGS2 were significantly higher in the fever group (p < 0.01)." (PMID 40430430, 2025).
Fever (continued). "Compared with the NG, the mRNA expressions of TNF-α, IL-6, IL-1β, NF-κB, TRPV4, and HSP70 in the MG were significantly upregulated (P < 0.01), indicating that the expression of mRNA was enhanced under fever conditions." (PMID 40356990, 2025). "The results demonstrated that the levels of ET-1, ICAM-1, TNF-α, IL-1β, MMP-9, NF-κB, NO, and TXB2 in yeast-induced fever in the model group rats were significantly higher than in the control group (P < 0.001)." (PMID 35178159, 2022). "Hyperthermia increases the amount of calreticulin in TME and consequently induces ICD.Hyperthermia increases the expression of IL‐6, IFN‐γ, and TNF‐α." (PMID 35908281, 2022). "Regardless immunoglobulin profile, all OROV fever patients presented higher levels of CXCL8, and IFN-α and lower levels of TNF and IL-10 at baseline as compared to healthy donors (HD)." (PMID 31784575, 2019). "Fever has been correlated with PMN infiltration into the lung, as well as with IFN-α, TNF-α, IL-1, and IL-6 production in response to SIV infection." (PMID 23074662, 2011). "Fever, hepatosplenomegaly, hyperferritinemia, and pancytopenia are common clinical manifestations of HLH, which are accompanied by increased levels of cytokines, such as interferons (IFNs), interleukin-1β (IL-1β), IL-18, IL-6, and tumor necrosis factor (TNF)." (PMID 40632844, 2025). "In contrast, TNF-α concentrations remained significantly higher in the fever group compared to both the no fever and control groups (p < 0.05)." (PMID 40508975, 2025). "For example, in children following rotavirus gastroenteritis, significantly increased serum levels of IL-6 and TNF have been reported in fever patients more than in those without." (PMID 37403122, 2023). "IL6, IL1, TNF-α, TGF-β and IFN-γ, endogenous pyrogens, leading to high pyrexia." (PMID 33173434, 2020). "Although Histoplasma infection stimulated the production of pyrogenic cytokines (i.e., IL-1β, IL-6, and TNF-α), pyrexia is not induced in mice." (PMID 29295913, 2018). "Sickness behavior is a physiological behavioral response principally induced and regulated by proinflammatory cytokines, including interleukin 1β (IL-1β), IL-6 and tumor necrosis factor (TNF)α, which act centrally to induce sickness behaviors, including pyrexia." (PMID 23497361, 2013). "Accordingly, children with fever have been found to have significantly elevated levels of serum IL-6 compared with control children, and those with fever and more episodes of diarrhea had significantly higher levels of TNF-α than those without fever and with fewer episodes of diarrhea." (PMID 36976000, 2023). "We found that LPS treatment could significantly increase the rectal temperature and dorsal interscapular surface temperature (contribute to fever) of mice, and the mRNA levels of TNFα, IL-6, Ucp1, and Pgc1α in the BAT, but did not affect the expression of Cpt1α and Cidea." (PMID 36430282, 2022). "The results showed that OROV fever patients presented higher levels of CXCL8 and IFN-α (pink background) and lower levels of TNF and IL-10 than HD (blue background), regardless of antibody profile at baseline." (PMID 31784575, 2019). "Therefore, our data indicate that metritic cows without a fever have an inherent lower inflammatory response with lower PMN function and lower production of TNFα despite a similar bacterial challenge to metritic cows with a fever." (PMID 27802303, 2016).